PPARA (peroxisome proliferator activated receptor alpha)
Diseases named in the same sentence as PPARA in open-access papers (continued):
Sharing a sentence is not in itself a finding about the gene and the disease.
cardiac hypertrophy (continued). "In the cardioprotective effects of apigenin, previous studies reported that PPARα and PPARγ were involved in ameliorating cardiac hypertrophy and myocardial abnormality." (PMID 36092543, 2022). "PPARα is also reported to contribute to the development of cardiovascular diseases including cardiac hypertrophy, heart failure, and diabetic cardiomyopathy through its regulation of fat metabolism." (PMID 35259201, 2022). "The expression of PPARA and PPARG significantly downregulated in myocardial hypertrophy, and activation of either PPARA or PPARG was able to inhibit the hypertrophic response." (PMID 35281609, 2022). "The several main regulators of PPARα such as HSF-1, ATGL, RXRα, and ERRα were detected, the downregulation of which are associated with cardiac hypertrophy." (PMID 35479323, 2022). "Studies have shown that PPARA and PPARG are closely associated with the development of myocardial hypertrophy." (PMID 35281609, 2022). "The dysfunction of peroxisome proliferator-activated receptor-α (PPARα) plays a key role in cardiac hypertrophy." (PMID 35479323, 2022). "Previous studies have shown that cardiac hypertrophy is closely related to the PPARα pathway, so we chose the PPARα signaling pathway as a candidate." (PMID 35383152, 2022). "As the predominant PPAR isoform in the heart, peroxisome proliferator-activated receptor α (PPARα) modulates cardiac metabolism substrate conversion in cardiac hypertrophy, cardiac hypoxia, and diabetic heart." (PMID 36291052, 2022). "Second, both cardiomyocytes-specific knockout and overexpression of PPARα induce cardiac hypertrophy in mouse hearts, which indicates the controversial role of PPARα in the development of cardiac hypertrophy." (PMID 35185581, 2022). "Fenofibrate-induced PPARα activation protects against endothelin-induced cardiac hypertrophy and failure through negative regulation of AP-1 binding activity." (PMID 36589809, 2022). "Statins have the potential to prevent cardiac hypertrophy through multifaceted activation of PPARα and PPARγ and by inhibiting inflammation and fibrosis." (PMID 35055179, 2022). "An in vitro study suggested that PPARα activation protects against cardiac hypertrophy and failure partly via inhibition of the JNK pathway." (PMID 36589809, 2022). "SIRT1 prevents cardiac hypertrophy, and protects against inflammation and metabolic dysregulation through interaction with PPARα and PGC1α." (PMID 33806509, 2021). "Definitive evidence demonstrates the critical requirement of peroxisome proliferator activated receptor (PPAR), particularly PPARα, in myocyte metabolism and metabolic reprogramming under cardiac hypertrophy." (PMID 34458345, 2021). "Here, mice exhibiting increased myocardial fatty acid oxidation rates and decreased glucose uptake and oxidation through the cardiac-restricted overexpression of PPARα resembled the phenotype of diabetic cardiomyopathy, including ventricular hypertrophy." (PMID 33673114, 2021). "Isoproterenol-induced cardiac hypertrophy was significantly attenuated by PPARα activation with fenofibrate or raspberry ketone, as indexed by altered hemodynamic and electrocardiogram patterns and enhanced oxidative stress." (PMID 34360540, 2021). "Altogether, these data illustrate that FABP3 participates in cardiac hypertrophy by synergistically activating Mlycd and Cpt1b and repressing Gck and Acaca via PPARα." (PMID 34458345, 2021). "Based on the expression profile and metabolic effects, the interactive effects of FABP3 and PPARα in cellular metabolism and cardiac hypertrophy were explored in this article." (PMID 34458345, 2021). "Specific knockout of PPARα results in cardiac hypertrophy and fat accumulation in rats, and ultimately heart failure leads to animal death." (PMID 35097008, 2021). "The PPARα/NRF2 signaling pathway protects the heart from remodeling induced by stress overload, and up-regulation of PPARα protein expression can improve cardiac hypertrophy." (PMID 35097008, 2021).
cardiac hypertrophy (continued). "We have demonstrated a beneficial value of FABP3 on cardiac hypertrophy and heart failure by inhibiting PPARα degradation." (PMID 34458345, 2021). "In the study, we investigated the protective effect of dapagliflozin on AAC-induced cardiac hypertrophy and its mechanism of involving activation of the Plin5/PPARα signaling axis." (PMID 34630108, 2021). "A previous study utilizing a systems biology approach investigating the sex differences in mice after angiotensin II‐induced hypertrophy found that inhibition of PPARα by a PPARα inhibitor blocked the sex differences in the development of cardiac hypertrophy." (PMID 32189431, 2020). "During myocardial ischemia-reperfusion and pressure-induced myocardial hypertrophy, PPARα is down-regulated." (PMID 33132907, 2020). "Nonetheless, in the present study we confirmed PPARα as a key regulator of cardiac hypertrophy and dysfunction in response to pressure overload, which influences both myocardial Nox2 expression and redox status." (PMID 32575797, 2020). "Energy substrate utilization showed a marked shift from fatty acid to glucose and lactate and cardiac hypertrophy in PPARα−/− hearts." (PMID 32028670, 2020). "The haploinsufficiency of either PPARα or SIRT1 reduces pressure overload-induced cardiac hypertrophy and failure, whereas the simultaneous induction of PPARα and SIRT1 aggravates cardiac dysfunction." (PMID 32708786, 2020). "In summary, 5-LOX inhibition by zileuton protects against cardiac hypertrophy, inflammation, and dysfunction in response to LV pressure overload by activating PPARα/NRF2 signaling in cardiomyocytes, which mediates oxidation balance." (PMID 31781348, 2019). "The opposite changes of PPARα and JNK1/2 also suggest PPARα was regulated by JNK1/2 signaling in the process of AB-induced cardiac hypertrophy." (PMID 29339422, 2019). "In response to transverse aortic constriction (TAC), PPARα-null mice showed pronounced cardiac hypertrophy." (PMID 30400386, 2018). "While fenofibrate had clear beneficial effects in wild-type mice, this drug had deleterious consequences on cardiac hypertrophy and fibrosis in PPARα−/− mice." (PMID 30400386, 2018). "Similar to PPARα, heart-specific PPARγ knockout mice developed cardiac hypertrophy with preserved normal cardiac metabolism and function." (PMID 30400386, 2018). "PPARα transgenic mice exhibited arrays of diabetic cardiomyopathy phenotypes including cardiac hypertrophy, systolic dysfunction, and reduced glucose uptake and oxidation." (PMID 30485307, 2018). "We also detect a repression of PGC1α/β and of PPARα mRNA after HFD-driven cardiac hypertrophy in WT animals whereas this tendency is not only spared but, rather, inverted in GRK2+/− mice." (PMID 27832814, 2016). "It has been shown that AMPK activation inhibited cardiac hypertrophy through the reactivation of PPARα signalling pathway." (PMID 26989860, 2016). "Activation of PPARα reduces cardiac hypertrophy, decreases cardiac fibrosis, attenuates cardiac dysfunction, and improves survival by inhibition of profibrotic, proinflammatory, and prohypertrophic genes." (PMID 27807394, 2016). "PPARα activator attenuates cardiac dysfunction, cardiac fibrosis, and cardiac hypertrophy; improves survival by regulating redox-regulated transcription factors; and causes suppression of profibrotic, prohypertrophic, and inflammatory genes in animals." (PMID 27807394, 2016). "Our findings provide a novel mechanistic insight into a role for PPARα and adiponectin in cardiac hypertrophy." (PMID 27807394, 2016). "PPARα is downregulated in response to cardiac hypertrophy, myocardial infarction, and heart failure associated with the decrease in fatty acid utilization." (PMID 27413362, 2016). "We also investigated the changes in SCAD and PPARα expression between pathological and physiological cardiac hypertrophy in vitro." (PMID 25753319, 2015).
cardiac hypertrophy (continued). "Tg-PPARα mice have mild cardiac hypertrophy, systolic dysfunction, and lipotoxicity, and over 50% die within 30 weeks." (PMID 26713088, 2015). "PPARα agonist WY14643 treatment of rats with cardiac hypertrophy and preserved cardiac power after ascending aortic constriction prevented energy substrate switching but decreased cardiac power." (PMID 26713088, 2015). "PPARα expression was elevated in hearts of trained rats and down-regulated in several models of pathological cardiac hypertrophy, concomitant with the switch from fatty acid to glucose utilization 17–19." (PMID 25753319, 2015). "Several cell- and rodent-based studies have demonstrated PPARα-dependent cardioprotection in the context of cardiac hypertrophy." (PMID 24523730, 2014). "It is known that transgenic mice with PPARα deletion develop a cardiac hypertrophy mimicking what is observed in the human diabetic condition." (PMID 23573121, 2013). "This ERK1/2 independent nuclear shuttling of PPARα by MEK1 provides an attractive explanation for the metabolic switch during cardiac hypertrophy and will lead to new insights into the different mechanisms between pathological and physiological hypertrophy." (PMID 22723831, 2012). "In a murine model of pressure overload-induced cardiac hypertrophy, reactivation of PPARα with an agonist resulted in severe depression of cardiac power and efficiency." (PMID 23049681, 2012). "In the future, strategies to upregulate or activate PPARα for the treatment of cardiac hypertrophy may have significant clinical translation potential." (PMID 40211903, 2025). "PPARα knockout (KO) mice exhibit severely impaired FAO and high glucose oxidation; conversely, PPARα transgenic mice show increased fatty acid uptake and oxidation capacity, with reduced glucose oxidation, ultimately leading to cardiac hypertrophy and heart function impairment." (PMID 40166465, 2025). "Both can promote fatty acid metabolism, but PPARα will reduce glucose intake and lower glycolysis levels, which may lead to lipid accumulation and myocardial hypertrophy." (PMID 40994651, 2025). "Our study further underscores the role and mechanism of PPARα in pathological cardiac hypertrophy." (PMID 40211903, 2025). "Additionally, after 8 weeks of TAC, Maresin1 alleviated PO‐induced cardiac hypertrophy and fibrosis, and promoted the deubiquitination and stabilization of PPARα through the PKG/CREB1/USP4 pathway." (PMID 40211903, 2025). "The decrease in CD36 in pathological cardiac hypertrophy and the upregulation in physiological cardiac hypertrophy may be related to PPARa." (PMID 40565598, 2025). "Overexpression of PPARα and USP4 ameliorated PO‐induced cardiac hypertrophy in Lgr6‐deficient mice." (PMID 40211903, 2025). "Among them, five signaling pathways, such as PPAR and PPARα/RXRα activation, were significantly downregulated, and the cardiac hypertrophy signaling, pulmonary fibrosis idiopathic signaling pathway, and S100 family signaling pathway were significantly upregulated." (PMID 39202454, 2024). "Similarly, as a regulator of cardiomyocyte FAO, knockout of PPARα worsened pressure overload-induced heart failure, while PPARα agonists improved pathological myocardial hypertrophy." (PMID 38346961, 2024). "PPARα is considered to be important in cardiac hypertrophy and fibrosis." (PMID 37221368, 2023). "Osthol could reduce rat cardiac hypertrophy by increasing PPARα mediated CPT-1a mRNA while decreasing DGAT mRNA." (PMID 35383152, 2022). "Finally, we found that MIAT was a necessary regulator of cardiac hypertrophy due to its regulation of the Ythdf2/PPARα/CPT-1a axis." (PMID 35383152, 2022). "Overexpressing PPARα in the heart can induce cardiac dysfunction and cardiac hypertrophy." (PMID 35259201, 2022). "PPARα gene deletion contributes to cardiac hypertrophy and deterioration of cardiac function." (PMID 36291052, 2022).
cardiac hypertrophy (continued). "Therefore, the regulation of PPARα function has become one of the important strategies against cardiac hypertrophy." (PMID 35479323, 2022). "Increased NOX2 protein expression has been correlated with cardiac hypertrophy and dysfunction development via downregulation of PPARa, action that could be reversed with fenofibrate (a PPARa activator) or NOX2 inhibitors in in vitro and in vivo mice models." (PMID 36012897, 2022). "Peroxisome proliferator-activated receptor α (PPARα) signaling was involved in cardiac hypertrophy." (PMID 35383152, 2022). "In this study, we demonstrated that MIAT influenced AngII-induced cardiac hypertrophy by regulating the expression of a key m6A RNA methylation enzyme, Ythdf2, and may influence its downstream target genes PPARα/CPT-1a." (PMID 35383152, 2022). "However, the utilization of heart’s energy substrate is switched from fatty acids to glucose in cardiac hypertrophy, and then the dysfunction of PPARα plays a key role in this process." (PMID 35479323, 2022). "Therefore, salidroside elevates ATGL expression and then generates more ligands for PPARα to inhibit cardiac hypertrophy." (PMID 35479323, 2022). "Also, PPARα-Sirt1 complex attributes to cardiac hypertrophy and failure by suppressing the ERR transcriptional pathway." (PMID 36385157, 2022). "Finally, to demonstrate the requirement of PPARα in FABP3 mediated cardiac hypertrophy, PPARα was knocked down using siRNA methods." (PMID 34458345, 2021). "When analyzed individually with IPA, the top FoxO dependent canonical pathways were most enriched for protein kinase A signaling, sirtuin signaling (which includes many OXPHOS and other mitochondrial genes), cancer-related, cardiac hypertrophy, PPARα/RXRα activation, and mitochondrial dysfunction." (PMID 35185597, 2021). "Additionally, treatment with the PPARα agonist, fenofibrate, effectively repressed Fabp3-KO induced cardiac hypertrophy, highlighting a potential clinical value of hypertrophic treatment by targeting cardiac energy metabolism." (PMID 34458345, 2021). "Numerous studies have reported the beneficial effect of activation of the PPARα signal on the development of cardiac hypertrophy, which may be attributed to its regulation of myocardial function and energy metabolism through modulating fatty acid oxidation." (PMID 34630108, 2021). "Furthermore, Fabp3 mediated the PPARα protein levels by directly binding to PPARα and preventing its degradation and underpinning its transactivation on Mlycd and Gck, which underscores the pivotal metabolic role of PPARα in FABP3-mediated cardiac hypertrophy." (PMID 34458345, 2021). "Both in vivo and in vitro experiments have confirmed that DAPA could mediate the Plin5/PPARα signaling axis to play a protective role in inhibiting cardiac hypertrophy." (PMID 34630108, 2021). "Considering the molecular mechanism of Plin5 and PPARα in cardiac hypertrophy, we hypothesized that DAPA might mediate the protective effect of Plin5/PPARα signaling axis." (PMID 34630108, 2021). "Moreover, KLF5 promotes cardiac hypertrophy and regulates peroxisome proliferator-activated receptor alpha (PPAR-α) expression." (PMID 34290289, 2021). "Furthermore, we demonstrated an inhibitory role of DAPA on cardiac hypertrophy by activating Plin5/PPARα signaling cascades in the myocardium." (PMID 34630108, 2021). "For example, PPARα activation with fenofibrate in hypertensive rats failed to prevent cardiac hypertrophy, although associated cardiac fibrosis and LV chamber dilatation were reduce." (PMID 32575797, 2020). "Furthermore, in rats subjected to pressure overload induced by abdominal aortic constriction for 7 days, PPARα activation resulted in a significantly worsened cardiac hypertrophy and systolic dysfunction, compared to untreated control animals." (PMID 32575797, 2020).
cardiac hypertrophy (continued). "Simultaneously, our previous study showed that PPARα could ameliorate cardiac hypertrophy and that PPARα expression could be induced by the activation of ERK1/2 signaling pathways." (PMID 29339422, 2019). "These evidence indicate that ANGPTL4 may be effective in inhibiting cardiac hypertrophy via the regulation of PPARα." (PMID 29339422, 2019). "Consistent with our previous studies, we discovered that PPARα expression is decreased in cardiomyocytes transfected with si-ANGPTL4 under PE stress, which suggested that PPARα could be one of the targets of ANGPTL4 in the regulation of cardiac hypertrophy." (PMID 29339422, 2019). "In addition, eNOS and glioma invasiveness signalling were more activated whereas LXR/RXR and PPARα/RXRα activation, GnRH (Gonadotropin Releasing Hormone) signalling, α-adrenergic, and cardiac hypertrophy signalling were significantly deactivated in aCDCs." (PMID 29915261, 2018). "Most studies show decreased PPARα after pressure overload induced cardiac hypertrophy." (PMID 26713088, 2015). "Moreover, AICAR-induced AMPK activation prevents the PPARα reduction in both in vitro and in vivo models of cardiac hypertrophy." (PMID 26649034, 2015). "Treatment of rats with the dual-PPARα/γ agonist LY510929 induced cardiac hypertrophy." (PMID 26713088, 2015). "For example, aortic constriction in Pparα−/− mice resulted in increased cardiac hypertrophy compared to WT mice and Pparα−/− mice on a high salt diet had an increased heart weight/body weight ratio compared to WT mice potentially demonstrating a greater afterload effect in Pparα−/−." (PMID 26649033, 2015). "In addition, activation of PPARα inhibited pathological cardiac hypertrophy via various signalling pathways 21,22." (PMID 25753319, 2015). "The deactivation of PPARα may result in the decrease in SCAD expression in pathological cardiac hypertrophy." (PMID 25753319, 2015). "Altered function of PPARα induces cardiac hypertrophy in mice." (PMID 25389966, 2014). "Furthermore, we provide insights into a possible mechanism of how PPARα suppresses the progression of cardiac hypertrophy, with HMGB1 involvement." (PMID 24523730, 2014). "Because fenofibrate, a peroxisome proliferator-activated receptor α (PPARα) agonist, has shown both protective effects against cardiac hypertrophy and inhibitory effects against inflammation, the potential modulation of HMGB1 expression and secretion by fenofibrate is of great interest." (PMID 24523730, 2014). "To determine whether the discovered mechanism of MEK1 mediated PPARα inhibition also occurred in vivo, we chose voluntary running-wheel exercise as a model to stimulate physiological cardiac hypertrophy and activate cardiac MEK1 in mice." (PMID 22723831, 2012). "The decline of protein expression and transcriptional activity of cardiac PPARα is widely observed in cardiac hypertrophy, and cardiac hypertrophy is enhanced in response to chronic pressure overload in mice of PPARα knockout; moreover, PPARα agonists can attenuate cardiac hypertrophy." (PMID 35479323, 2022). "In addition, PPARα agonist elevates its function to alleviate cardiac hypertrophy." (PMID 35479323, 2022). "Besides, H19 has been identified as a regulator that targets PPARα of cardiac hypertrophy." (PMID 34362365, 2021). "Finally, we investigated whether dapagliflozin mediated the Plin5/PPARα signaling axis to exert a protective effect against cardiac hypertrophy." (PMID 34630108, 2021). "Immunoblotting results suggested that the impaired expression levels of mitochondrial synthesis-associated proteins (PGC1α, ERRα, PPARα, and CD36) could be partially rescued by AAV9-Sesn2 treatment in aged WT (Aged) mice that had been subjected to pressure overload-induced cardiac hypertrophy." (PMID 32863202, 2020). "In addition, some experiments found that gene expression of PPARα was reduced in pathological cardiac hypertrophy, suggesting that upregulation of PPAR-α expression may limit pathological cardiac hypertrophy." (PMID 32848751, 2020).